DDX41 (DEAD-box helicase 41)
Diseases named in the same sentence as DDX41 in open-access papers (continued):
Sharing a sentence is not in itself a finding about the gene and the disease.
viral infection (11 papers, 2018 to 2025). "Collectively, these data indicate that fish Ddx41 senses DNA, RNA or viral infection, thereby activating STING-dependent immune responses." (PMID 39185415, 2024). "Upon virus infection, DDX41 binds STING, leading to phosphorylation of TBK1 and IRF3, and the production of type I IFN." (PMID 39185415, 2024). "DDX41, a member of the DExD/H-box helicase superfamily, is involved in intracellular DNA recognition and triggers innate immune responses against viral infection." (PMID 36680100, 2022). "DDX41 is a member of the DExD/H-box helicase superfamily and acts as an intracellular DNA sensor which triggers the innate immune response against viral infection in mammalian cells." (PMID 31552028, 2019). "However, the interaction between TRIM21 and DDX41 contributes to immune suppression during virus infection." (PMID 36675197, 2023). "TRIM21 mediates the polyubiquitination and degradation of the DNA sensor DDX41 and the IRF transcription factors IRF3, IRF5, and IRF7 to negatively regulate the production of interferon-β during viral infection." (PMID 33061806, 2020). "Grass carp DDX41 and SAMHD1 are located in the nucleus, but they are translocated from the nucleus to the cytoplasm in response to virus infection." (PMID 33488591, 2020). "In non-mammalian species, Ddx41 also plays a critical role in innate immune signaling and the response to viral infection and DNA or RNA stimuli." (PMID 39185415, 2024). "Therefore, the ubiquitination of IRF3/7 or its upstream sensors by TRIM21, such as STING, DDX41, NMI/IFI35, and RIG-I, leads to immune suppression during virus infection." (PMID 36675197, 2023). "DDX41 is an intracellular DNA sensor that evokes type I interferon (IFN-I) production via the adaptor stimulator of interferon gene (STING), triggering innate immune responses against viral infection." (PMID 36680100, 2022). "We showed previously that DCs get infected by MLV, and here, we demonstrate that DDX41 in DCs but not macrophages was required for in vivo control of virus infection." (PMID 29871919, 2018). "In contrast, DDX41 is not IFN-inducible in mammals, and its expression is not induced by viral infection or LPS in mammalian cells." (PMID 39185415, 2024).
leukemia (8 papers, 2020 to 2024). A malignant (clonal) hematologic disorder, involving hematopoietic stem cells and characterized by the presence of primitive or atypical myeloid or lymphoid cells in the bone marrow and the blood. "The correlation between DDX41 mutations and MDS/AML was further confirmed in 2017 when two donor cell leukemia cases attributed to DDX41 mutations were reported." (PMID 38348889, 2024). "Numerous variants in DEAD-box Helicase 41 (DDX41) have been identified in diverse blood disorders including leukemia." (PMID 37685935, 2023). "Early identification of stem-cell transplant donors in the family for patients with DDX41 mutations is crucial to avoid donor-derived leukemia from germline carriers." (PMID 36672294, 2023). "It is also important to note that our analysis of the effect of partial reduction in DDX41 expression in leukemia cells (MOLM13 cells) was conducted in a transient setting, with analysis occurring 4–6 days post-transduction." (PMID 38937548, 2024). "We identified distinct trajectories of leukemia development, providing support for the new ICC AML disease categories as well as for DDX41 mutations defining a new clinico-pathologic entity of AML." (PMID 37591941, 2023).
bone marrow failure syndrome (6 papers, 2016 to 2024).
platelet disorder (6 papers, 2021 to 2025). "These rare disorders are characterized by either CEBPA or DDX41 mutations and are often inherited in families without a pre-existing platelet disorder or organ dysfunction." (PMID 38473358, 2024).
chronic myelomonocytic leukemia (4 papers, 2016 to 2023). A myelodysplastic/myeloproliferative neoplasm which is characterized by persistent monocytosis, absence of a Philadelphia chromosome and BCR/ABL fusion gene, fewer than 20 percent blasts in the bone marrow and blood, myelodysplasia, and absence of PDGFRA or PDGFRB rearrangement. "DDX41 mutations have been described in approximately 1–3% of MDS/AML patients and are also described to a lesser extent in multiple myeloma, lymphoma, chronic myelomonocytic leukemia (CMML), and myeloproliferative neoplasms (MPNs)." (PMID 33585199, 2020).
melanoma (4 papers, 2020 to 2025). A malignant, usually aggressive tumor composed of atypical, neoplastic melanocytes. "First, while DDX41 primarily associates with hematological neoplasia, solid malignancies, especially prostate cancer, colorectal cancer, and melanoma, have been reported in individuals with pathogenic germline variants of DDX41." (PMID 37696923, 2023). "Meanwhile, the anti-melanoma effects induced by NAT10-knockout were also diminished in overexpressed DDX41 and ZNF746 levels in NAT10-KD cells." (PMID 39246323, 2024). "Gain- and loss-of-function experiments in NAT10, or in DDX41 and ZNF746, altered the chemosensitivity of melanoma accordingly, and the two target genes also negatively correlated with clinical outcomes." (PMID 39246323, 2024). "We further constructed DDX41-overexpressing (DDX41-OE) and ZNF746-overexpressing (ZNF746-OE) melanoma cells to evaluate whether anti-melanoma effects of Remodelin are mediated by DDX41 and ZNF746." (PMID 39246323, 2024). "In summary, our data disclose the role of NAT10 in DTIC resistance of melanoma cells, elucidate the machinery through mediating ac4C modification of DDX41 and ZNF746 mRNAs, and shed light on developing new therapeutic strategies using Remodelin and DTIC for melanoma treatment." (PMID 39246323, 2024). "In melanogenesis and melanoma (SKCM), suppressing NAT10 inhibits the chemoresistance of melanoma by reducing the expression of the C2H2-ZF family members DDX41 and ZNF746, respectively." (PMID 41316475, 2025). "We measured the protein levels of DDX41 and ZNF746 in our established DR melanoma cells, revealing that increased NAT10 was correlated with elevated DDX41 and ZNF746 proteins." (PMID 39246323, 2024). "Intriguingly, we found that when DDX41 or ZNF746 expression was forcibly expressed, the anti-melanoma effects of Remodelin were largely diminished in DDX41-OE and ZNF746-OE cells." (PMID 39246323, 2024). "Remarkably, immunohistochemical staining for NAT10, DDX41, and ZNF746 protein on tumor tissues from melanoma patients showed that NAT10 had a positive correlation with these two proteins." (PMID 39246323, 2024). "In this study, we disclosed an important role of NAT10 in DTIC resistance of melanoma, mechanistically through promoting NAT10-mediated ac4C modification of DDX41 and ZNF746 mRNAs." (PMID 39246323, 2024). "Follow-up analysis also indicated that DDX41 and ZNF746 expressions were negatively correlated with OS and progression-free survival (PFS) of melanoma patients." (PMID 39246323, 2024). "The following studies confirmed the correlation between DDX41 and ZNF746 expression and melanoma cell drug resistance as well as disease progression in patients." (PMID 39246323, 2024). "Collectively, these data suggest that DDX41 and ZNF746 are correlated with NAT10 expression and play a pivotal role in the treatment response and clinical outcomes of melanoma patients." (PMID 39246323, 2024). "Intriguingly, ac4C peaks on DDX41 and ZNF746 of melanoma cells were abolished upon NAT10 knockdown." (PMID 39246323, 2024). "Other tested DNA sensors (Cgas, Sting, Ddx41, Dhx9, Dhx36, Lrrfip1, Mre11, and additionally Aim2, which is absent in melanoma cells) were expressed in macrophages but were not significantly upregulated after irradiation." (PMID 33202881, 2020). "Furthermore, knockdown of DDX41 and ZNF746 sensitized melanoma cells to DTIC treatment." (PMID 39246323, 2024). "Furthermore, we investigated the mechanism of NAT10 promoting the mRNA ac4C modification of C2H2 zinc finger family members DDX41 and ZNF746 in chemoresistance of melanoma and finally evaluated the translational significance of NAT10 inhibitor in overcoming chemoresistance in vitro and in vivo." (PMID 39246323, 2024).
Myelodysplasia (4 papers, 2022 to 2026). Clonal hematopoietic stem cell disorders characterized by dysplasia (ineffective production) in one or more hematopoietic cell lineages, leading to anemia and cytopenia. "Mutated DDX41 improved the survival in “AML NOS” and was also associated with improved outcome within the category of “AML with myelodysplasia-related gene mutations”." (PMID 37591941, 2023).
anemia (3 papers, 2020 to 2025). A reduction in the number of red blood cells, the amount of hemoglobin, and/or the volume of packed red blood cells. "DDX41’s role in erythropoiesis is underscored by studies in zebrafish, where its deficiency leads to anemia through ineffective erythropoiesis, involving DNA damage response pathways." (PMID 40764304, 2025). "The majority of patients (66%) with germline DDX41 variants had a known prior history of antecedent cytopenias: twelve with leukopenia, four with anemia, and six had bicytopenias (most often leukopenia and anemia)." (PMID 33585199, 2020). "The only significant difference observed in Ddx41+/f;Vav-Cre+ mice was a consistent reduction in red blood cell (RBC) count across the lifespan that did not meet the criteria for clinical anemia." (PMID 38937548, 2024).
Fanconi anemia (3 papers, 2021 to 2025). Fanconi anemia (FA) is a hereditary DNA repair disorder characterized by progressive pancytopenia with bone marrow failure, variable congenital malformations and predisposition to develop hematological or solid tumors. "At our single institution, we had a yield of 14% (6/43) for patients with MDS or AML who were found to have a PV predisposing to myeloid disease (Fanconi Anemia, DKC1, DDX41, GATA2, TERC, and RUNX1)." (PMID 40936482, 2025).
acute lymphoblastic leukemia (2 papers, 2021 to 2024). Leukemia with an acute onset, characterized by the presence of lymphoblasts in the bone marrow and the peripheral blood. "Recent reports describe the development of acute lymphocytic leukemia and solid cancers in individuals with DDX41 variants, but the extent to which DDX41 variants are involved in such diseases remains controversial." (PMID 38203823, 2024).
hepatocellular carcinoma (2 papers, 2024). A malignant tumor that arises from hepatocytes. "Notably, higher levels of DDX41 were found in many types of solid tumors; in hepatocellular carcinoma, elevated expression of DDX41 correlated with increased tumor grade while in clear cell renal cell carcinoma, increased DDX41 was associated with tumor growth and poor prognosis." (PMID 39185415, 2024). "Hypoxia induced expression of DDX41 through HIF-1, making hypoxic hepatocellular carcinoma (HCC) cells more sensitive to the antimitotic agents in STING activation and SASP production." (PMID 39388278, 2024).
lymphoid neoplasm (2 papers, 2021 to 2023). A neoplasm composed of a lymphocytic cell population which is usually malignant (clonal) by molecular genetic and/or immunophenotypic analysis. "Finally, the possible contribution of germline mutations, including DDX41, RUNX1, ETV6, ANKRD26, and POT1, which have been associated with the occurrence of both myeloid and lymphoid neoplasms, is an intriguing point to be explored in future studies." (PMID 34733777, 2021).
multiple myeloma (2 papers, 2020 to 2022). "Additionally, lymphoid malignancies were not screened for somatic DDX41 mutations and therefore potential germline carriers with lymphoma and/or multiple myeloma may have been missed." (PMID 33585199, 2020).
myeloproliferative neoplasm (2 papers, 2023 to 2026). A clonal hematopoietic stem cell disorder, characterized by proliferation in the bone marrow of one or more of the myeloid (i.e., granulocytic, erythroid, megakaryocytic, and mast cell) lineages. "Single acquired DDX41 variants on their own were not identified as major contributors to the pathophysiology of AML, MDS and myeloproliferative neoplasms (MPN)." (PMID 37434984, 2023).
Parkinson disease (2 papers, 2024). A progressive degenerative disorder of the central nervous system characterized by loss of dopamine producing neurons in the substantia nigra and the presence of Lewy bodies in the substantia nigra and locus coeruleus. "Microglia in the brain has garnered significant attention in the research of DDX41, and it is believed that microglial DDX41 plays a role in neurodegenerative diseases such as ALS and Parkinson’s disease." (PMID 38467840, 2024).
acromesomelic dysplasia (1 paper, 2024). A group of extremely rare, inherited, progressive skeletal conditions that result in a particular form of short stature, called short-limb dwarfism. "These gene-specific alterations may explain the development of characteristic phenotypes such as acromesomelic dysplasia in the patient, while genome-wide changes indicate global deleterious consequences of DDX41 deficiency." (PMID 39453476, 2024).
adenovirus infection (1 paper, 2022). "However, studies on the molecular steps that lead to the activation of and signaling by DDX41 during adenovirus infection would provide an insight into this pathway, which has not been yet fully characterized." (PMID 35458396, 2022).
age (1 paper, 2024). A temporal measurement of the time period elapsed since an identifiable point in the life cycle of an organism.
amyotrophic lateral sclerosis (1 paper, 2024). Amyotrophic lateral sclerosis (ALS) is a neurodegenerative disease characterized by progressive muscular paralysis reflecting degeneration of motor neurons in the primary motor cortex, corticospinal tracts, brainstem and spinal cord. "Independent of infection, in a model of misfolded mutant Superoxide dismutase (SOD1)-driven amyotrophic lateral sclerosis (ALS), damaged mitochondria-released mtDNA and mt(DNA/RNA) hybrids activated the cGAS-STING and DDX41-STING pathways, respectively." (PMID 39185415, 2024).
B-cell lymphoblastic leukemia (1 paper, 2022). "We report a novel case of bi-alleleic DDX41 mutations in B-cell lymphoblastic leukemia (B-ALL), with unusual location of DDX41 mutations." (PMID 35246110, 2022).
breast carcinoma (1 paper, 2024). "In breast cancer, lower patient survival rate was linked to higher expression of DDX41 and endogenous DDX41 in a breast cancer cell line promoted cell growth and colony forming capacity." (PMID 39185415, 2024).
cervical dysplasia (1 paper, 2019). "DDX41 encodes an ATP-dependent RNA helicase and variants predispose to myeloproliferative/lymphoproliferative neoplasms (OMIM #616871) and thus may be related to cervical dysplasia in the patient." (PMID 32047491, 2019).
diabetes (1 paper, 2025). "In this review, we summarize the current knowledge on the roles of TLR9, cGAS‐STING, AIM2, IFI16, DNA‐PK, and DDX41 in obesity, diabetes, fatty liver disease, and cardiovascular disease." (PMID 39158380, 2025). "Although current research does not extensively cover the direct involvement of DDX41 in metabolic diseases such as obesity, diabetes, fatty liver diseases, or cardiovascular diseases, there are emerging lines of evidence suggesting its broader relevance." (PMID 39158380, 2025).
germ cell tumor (1 paper, 2023). A benign or malignant, gonadal or extragonadal neoplasm that originates from germ cells. "Interestingly RNA helicases DHX36 and DDX41 were inhibited in DSD-GCT (labeled green), potentially implying the redundant role of RNA regulation in innate immune response induction in patients with germ cell tumor." (PMID 37217472, 2023).
herpesvirus infection (1 paper, 2019). "Additionally, DNA-dependent activator of IFN-regulatory factors (DAI), DNA-dependent protein kinase (DNA-PK) and DEAD box helicase 41 (DDX41) are implicated in sensing herpesvirus DNA, but their exact functions in herpesvirus infection are not well understood." (PMID 31234396, 2019).
ichthyosis (1 paper, 2024). Disorders of cornification that are characterized by visible scaling and/or hyperkeratosis of most or all of the skin. "Here, we report a patient who inherited compound heterozygous DDX41 variants and presented with bone dysplasia, ichthyosis, and dysmorphic features." (PMID 39453476, 2024). "In this study, we identify biallelic germline variants in the DDX41 gene in a patient with bone dysplasia, ichthyosis, and dysmorphic features." (PMID 39453476, 2024).
leiomyosarcoma (1 paper, 2024). An uncommon, aggressive malignant smooth muscle neoplasm, usually occurring in post-menopausal women.
leukopenia (1 paper, 2020). "Several studies have demonstrated antecedent cytopenias, particularly leukopenia, in germline DDX41 mutation carriers." (PMID 33585199, 2020).
lung carcinoma (1 paper, 2021). "Small molecule inhibitors have been successfully developed to target the DEAD‐box RNA helicases eukaryotic initiation factor‐4A, DEAD‐box RNA helicase 3 (DDX3), and DDX41, with the DDX3 inhibitor RK‐33 now in clinical trials for lung cancer patients." (PMID 33497018, 2021). "Small molecule inhibitors of DDX21 could be developed with helicase targeting strategies similar to the discovery of DDX3 and DDX41 inhibitors, one of which (DDX3 inhibitor, RK‐33) is currently in a clinical trial in lung cancer patients." (PMID 33497018, 2021).
macrocytic anemia (1 paper, 2025). Anemia that is characterized by increased red blood cell volume. "They showed mild macrocytic anemia with normal white blood cell and platelet counts at 2 months old, which partially mimics patients with DDX41 germline mutations before the development of overt MNs upon somatic second hit8,24,25." (PMID 40764304, 2025).